ANPEP (alanyl aminopeptidase, membrane)
Diseases named in the same sentence as ANPEP in open-access papers (continued):
Sharing a sentence is not in itself a finding about the gene and the disease.
gastric cancer (11 papers, 2017 to 2024). A primary or metastatic malignant neoplasm involving the stomach. "Similarly, ANPEP showed higher progression in stomach cancer and reduced survival in stomach cancer, and lower expression levels in colon and lung tumors with reduced survival in colon patients." (PMID 39542983, 2024). "We observed an increased expression of ACE2, DPP4, ANPEP, and ENPEP in renal tumor data available on TCGA followed by gastrointestinal cancers such as colorectal, pancreatic, and stomach cancer." (PMID 33330620, 2020).
multiple myeloma (10 papers, 2014 to 2024). "Melflufen could be hydrolyzed to its active form by the aminopeptidases LAP3, LTA4H, RNPEP, and ANPEP, all of which are expressed in multiple myeloma." (PMID 33810334, 2021).
type 2 diabetes (10 papers, 2015 to 2025). "Potential mechanisms underlying the relationship between type 2 diabetes and the ANPEP gene may involve the disruption of redox homeostasis and glutathione metabolism." (PMID 40949127, 2025). "This suggests that increased expression of ANPEP leads to an increased risk of type 2 diabetes." (PMID 26825526, 2016). "The observation that current smoking, which increases the risk of type 2 diabetes, may lead to higher gene expression levels of ANPEP is in line with the observation of Locke and colleagues." (PMID 26825526, 2016). "ANPEP has been associated with regulating networks involved in the development of type 2 diabetes and may underlie pancreatic β cell fate during metabolic stress." (PMID 26375667, 2015). "The observation that DNA sequence variation and DNA methylation at this locus is associated with increased expression levels of ANPEP suggests a role for ANPEP in the pathogenesis of type 2 diabetes, rather than the gene AP3S2 proposed by prior GWAS." (PMID 26825526, 2016). "In another study, allele-specific expression of several genes in islets (ANPEP, CAMK2B, HMG20A, KCNJ11, NOTCH2, SLC30A8 and WFS1) showed that even subtle changes of gene dosage may have significant consequences for development of type 2 diabetes." (PMID 30497374, 2018).
renal carcinoma (9 papers, 2010 to 2024). A carcinoma arising from the epithelium of the renal parenchyma or the renal pelvis. "Recent studies revealed that other SARS-CoV-2 factors such as ANPEP (alanyl aminopeptidase, membrane), ENPEP (glutamyl aminopeptidase), and DPP4 (dipeptidyl peptidase 4) are expressed at high levels in renal cancer, especially in ccRCC." (PMID 38255667, 2023). "Further analysis of renal carcinoma subtypes revealed that KIRP and KIRC tumors exhibit increased levels of DPP4, ANPEP, and ENPEP along with ACE2 receptors." (PMID 33330620, 2020). "We further analyzed the expression of ACE2, ANPEP, ENPEP, DPP4, and TMPRSS2 gene in renal carcinoma tissues." (PMID 33330620, 2020). "But ANPEP is not suitable as a therapeutic target in renal carcinoma." (PMID 32127786, 2020).
diabetes (8 papers, 2015 to 2025). "By comparing the direct overlap between the heterogeneous islet diabetes-related gene sets we identified genes such as ANPEP and HADH that are currently not well-established as diabetes susceptibility genes but had consensus support across evidence sources." (PMID 28473845, 2017).
Cirrhosis (6 papers, 2019 to 2025). A chronic disorder of the liver in which liver tissue becomes scarred and is partially replaced by regenerative nodules and fibrotic tissue resulting in loss of liver function. "This study also allowed for the association of aminopeptidase N (ANPEP) and transforming growth factor-beta-induced protein ig-h3 (TGFB1) with NAFLD and cirrhosis." (PMID 36144184, 2022). "Furthermore, a global correlation map of clinical and proteomic data strongly associated DPP4, ANPEP, TGFBI, PIGR, and APOE with NAFLD and cirrhosis." (PMID 30824564, 2019). "ANPEP expression is upregulated in the plasma of patients with nonalcoholic fatty liver disease (NAFLD) and cirrhosis, suggesting that it may be involved in the progression of NAFLD and may serve as a potential drug target." (PMID 40630623, 2025).
osteosarcoma (6 papers, 2018 to 2023). A usually aggressive malignant bone-forming mesenchymal neoplasm, predominantly affecting adolescents and young adults. "On the contrary, our study showed that ANPEP expression of good chemotherapy response samples was approximately two times that in chemoresistance osteosarcoma samples." (PMID 29850522, 2018). "Among them, MAN2B1, P4HA2, ANPEP, BCAT1, CTSS, and DAPK1 were significantly correlated with the prognosis of patients with osteosarcoma." (PMID 37457661, 2023). "The relative expression levels of IGFBP4, SERPINE1, ANPEP and TAGLN were significantly lower in the osteosarcoma group compared with the normal group." (PMID 35665757, 2022). "And LYN, TNC, TGFB2, IGFBP1were up-regulated in the osteosarcoma tissue samples, while IGFBP4, TAGLN, SERPINE1, ANPEP were down-regulated." (PMID 35665757, 2022). "Among them, hsa-miR-543, as well as ZNRD1, GPR68, CAT, FUT3, ANPEP, and CDK1 genes, were proposed as crucial players in osteosarcoma chemoresistance, and hence they could represent potential therapeutic targets for osteosarcoma." (PMID 35011442, 2021). "And many of them, such as ZNRD1, GPR68, CAT, FUT3, ANPEP, CDK1, and hsa-miR-543, might be key genes related to osteosarcoma chemoresistance." (PMID 29850522, 2018).
squamous cell carcinoma (6 papers, 2017 to 2025). A carcinoma arising from squamous epithelial cells. "However, ANPEP expression in endothelial cell and vessel-associated stroma cell had positive prognostic effect on NSCLC patients with squamous cell carcinoma, and with negative prognostic effect on tumor stage III patients, and for patients with pN2 lymph node status." (PMID 34633989, 2021).
glioblastoma (5 papers, 2021 to 2025). The most malignant astrocytic tumor (WHO grade IV). "In fact, the BS149 cell line generated from recurrent glioblastoma is more malignant than the other four glioblastoma cell lines (LN018, LN215, LN229, and LN319) and has higher mRNA levels of DPP4, ANPEP, and ENPEP, further corroborating the potential oncogenic roles of ANPEP and ENPEP in GBM." (PMID 35464443, 2022).
acute renal failure (4 papers, 2015 to 2024). "Among the targets of RAAS inhibitors, PTGS2, ITGA4 and ANPEP have a causal relationship with acute kidney injury, which is worthy of further clinical research." (PMID 38332893, 2024). "According to our findings, ANPEP serves as a protective factor against acute renal failure in DN patients treated with RAAS inhibitors." (PMID 38332893, 2024).
B-cell acute lymphoblastic leukemia (4 papers, 2015 to 2023). A neoplasm of lymphoblasts committed to the B-cell lineage, typically composed of small to medium-sized blast cells. "For example, aminopeptidase N (ANPEP alias CD13) is abnormally expressed in AML, B-cell acute lymphoblastic leukemia, and chronic lymphoblastic leukemia, where it may be used as a diagnostic or prognostic marker." (PMID 33810334, 2021).
depression (4 papers, 2017 to 2025). "Additionally, PTPN6, STIP1, ANPEP, and TSPYL1 were found to be correlated with major depressive disorder." (PMID 40520536, 2025).
osteoarthritis (3 papers, 2014 to 2016). A noninflammatory degenerative joint disease occurring chiefly in older persons, characterized by degeneration of the articular cartilage, hypertrophy of bone at the margins and changes in the synovial membrane. "We also confirmed the expression of ANPEP, dickkopf WNT signaling pathway inhibitor 3 (DKK3) and osteoglycin (OGN) by multiple reaction monitoring (MRM) analysis of osteoarthritis synovial fluid samples." (PMID 24533825, 2014).
liver disease (2 papers, 2019 to 2023). "However, nothing is known about a possible role of TFGBI and ANPEP in liver disease." (PMID 30824564, 2019). "The other four are also highly relevant for liver disease: APOE (apolipoprotein E), dipeptidyl peptidase‐4 (DPP4), TGFBI (transforming growth factor‐beta‐induced protein ig‐h3), and aminopeptidase N (ANPEP)." (PMID 30824564, 2019). "Remarkably, in this unbiased analysis, four clinical markers used in liver disease—ALT, AST, ALP, and GGT—clustered into a single group together with a panel of five proteins of special interest—PIGR, DPP4, ANPEP, TGFBI, and APOE." (PMID 30824564, 2019). "In addition, many novel liver disease biomarkers were discovered, such as EGF-containing fibulin-like extracellular matrix protein 1 (EFEMP1), SAA2, CPN2, ANPEP, TGFBI, and FGG." (PMID 37209815, 2023).
Ascites (1 paper, 2023). Accumulation of fluid in the peritoneal cavity (between the layers of the peritoneum that lines the abdomen). "For example, ANPEP is a target of the drug, Icatibant, which is used to treat refractory ascites in patients with LC." (PMID 37209815, 2023).
heart failure (1 paper, 2025). Inability of the heart to pump blood at an adequate rate to meet tissue metabolic requirements. "However, ANPEP expression is downregulated in sacubitril/valsartan-resistant (SVR) patients with heart failure, indicating that it may be involved in the development of SVR and serve as a potential therapeutic target or biomarker." (PMID 40630623, 2025).
intestinal cancer (1 paper, 2024). "ANPEP has not been as widely studied, especially in the context of intestinal cancer development with varied iron intake, but it has been observed that ANP/ANPEP is downregulated in tumorigenic prostate cell lines." (PMID 38732562, 2024).
mood disorder (1 paper, 2025). A cognitive disorder a disturbance in which the person's mood is hypothesized to be the main underlying feature. "The pseudogene CCNB3P1 may affect self-harm via neuronal health, and ANPEP influences neuropeptide metabolism linked with mood disorders." (PMID 40125487, 2025).
preeclampsia (1 paper, 2015). Preeclampsia is a hypertensive disorder of pregnancy that is characterized by new-onset hypertension with proteinuria presenting after 20 weeks of gestation, and depending on mild or severe forms may initially present with severe headache, visual disturbances, and hyperreflexia. "The mRNA, protein and the activity of ANPEP is known to be higher in human placentae of pregnancies complicated with preeclampsia compared to normal pregnacy." (PMID 26260700, 2015).
Renal cyst (1 paper, 2024). A fluid filled sac in the kidney. "We found that multiple genes encoding enzymes in the γ-glutamyl cycle were highly downregulated in renal cysts, including γ-glutamyl transferase (GGT1, −14×), dipeptidase 1 (DPEP1, −32.5×), aminopeptidase N (ANPEP, −12×) and 5-oxoprolinase (OPLAH, −2.6×)." (PMID 39000280, 2024).
renal tumors (1 paper, 2017). "In renal tumors, enhanced ANPEP expression correlates with poor survival of patients, while high CYR61 levels stimulate proangiogenic activity of cancer cells." (PMID 29272308, 2017).
sarcoidosis (1 paper, 2025). Sarcoidosis is a multisystemic disorder of unknown cause characterized by the formation of immune granulomas in involved organs. "While MET is a hallmark of tissue granuloma formation, blood monocytes in both active TU and sarcoidosis exhibited epithelial–mesenchymal transition (EMT) signatures, including significantly increased expression of GADD45B, CD44, CXCL8, ANPEP and THBS1,30, 31, 32, 33 compared with healthy donors." (PMID 40469525, 2025).
steatosis (1 paper, 2025). Increased lipid within the cytoplasm of cells. "Specifically, H4C1, OIT3, ANPEP, CCDC25 and KLHL41 were identified as potential biomarkers for steatosis, GP1BA as a candidate marker for MASH and C7, IGHD and GNB1 as potential biomarkers for fibrosis severity." (PMID 41301514, 2025).
thyroid tumor (1 paper, 2023). A benign or malignant neoplasm affecting the thyroid gland. "In an independent validation set (GSE60542), we noted significant differential expression of 11 of the 12 previously identified hub genes, with the exception of ANPEP, between normal thyroid tissue and thyroid tumors." (PMID 38144565, 2023).
upper respiratory tract infections (1 paper, 2020). "Our study on ACE2 provides a systematic road map to redesigning an entry receptor as a therapeutic, and we believe the same strategy could be applied to other entry receptors such as DPP4 for treating MERS and aminopeptidase N (ANPEP) for treating upper respiratory tract infections by HCoV-229E." (PMID 33093202, 2020).
tumor (347 papers, 2002 to 2026). "We found in our present study that ANPEP is associated with EOCRC in terms of its gene expression in tumor tissue." (PMID 36748835, 2023). "Over-expression of ANPEP has been linked with tumor size, differentiation and metastasis in pancreatic, gastric, breast and gallbladder cancers." (PMID 36366359, 2022). "In this study univariate prognostic models showed that tumor cells ANPEP mRNA expression was associated with increased over-all survival." (PMID 34633989, 2021). "Moreover, a low expression of ANPEP has been reported as a target associated with malignant transformation and tumor cell invasion in CRC." (PMID 36748835, 2023). "Four of these genes were expressed greater than 10-fold in tumor tissue: ANPEP mRNA exhibited a significant (Adj." (PMID 41465326, 2025). "ANPEP (aminopeptidase N/CD13) is a multifunctional enzyme with significant roles in cancer biology, influencing tumor progression, angiogenesis, immune modulation, and therapeutic resistance." (PMID 41465326, 2025). "Consistently, the lower expression levels of ANPEP observed in primary tumor tissues of CRC and UC patients further substantiate this phenomenon." (PMID 39542983, 2024). "ANPEP protein expression was assessed in randomly selected tumor tissues from 12 CRC patients (six patients each EOCRC and LOCRC) in the validation cohort." (PMID 36748835, 2023). "In comparisons of the normal and tumor tissues in public datasets, the ANPEP level was significantly lower in the tumor tissue in the TCGA dataset (p < 2.2 × 10−16) and GSE196006 dataset (p = 0.0005)." (PMID 36748835, 2023). "The three remaining genes represented two solute carrier transporters (SLC27A1 and SLC7A5) for amino acids and fatty acids and one membrane bound protease (ANPEP) that plays a role in tumour invasion and metastasis." (PMID 37495601, 2023). "The cg26222247 probe, one of these four sites, was found to be hypermethylated in tumor tissue compared with normal tissue, and its methylation level correlated negatively with the ANPEP expression level (R = −0.21, p = 0.00011)." (PMID 36748835, 2023). "Based on the results, the level of ANPEP, HLA‐A, CCL2, TLR4 and SERPINE1 had statistically significant association with tumor purity in UCEC tissues." (PMID 36969077, 2023). "We first verified that ANPEP expression was lower in tumor tissues than in normal tissues in the TCGA dataset (Wilcoxon test, p < 2.2 × 10−16)." (PMID 36748835, 2023). "According to the NCBI, defects in the ANPEP gene enhances angiogenesis, tumor growth, and metastasis." (PMID 35547358, 2022). "ANPEP is also found to be overexpressed in tumor tissue of several cancers contributing to tumor progression, proliferation, tumor invasion and angiogenesis." (PMID 34876625, 2021). "Some of the tumor-associated proteins with differential levels in comparison to all the control types include 5′-nucleotidase isoform 2 (NT5E), aminopeptidase N (ANPEP)." (PMID 34876625, 2021). "Other literatures suggested ANPEP was a therapeutic target or prognostic marker of other tumors, that indicated its role in tumor malignancy." (PMID 32756007, 2020). "ANPEP is the membrane-bound metalloproteases for general protein hydrolysis and also involved in cancerogenesis and tumor angiogenesis." (PMID 32756007, 2020). "It’s interesting that ANPEP downregulation reduced cell growth and cell invasiveness but resulted in elevated xenograft tumor growth." (PMID 32756007, 2020). "They showed that ANPEP was upregulated in endothelial tumor cells and expressed in blood vessels undergoing angiogenesis." (PMID 32756007, 2020). "Within the tumor microenvironment, ANPEP expression is induced by vascular endothelial growth factor (VEGF), and high levels of CD13 have been associated with tumor progression in breast, ovarian, and prostate cancers." (PMID 27786256, 2016).